CD4 (CD4 molecule)
Diseases named in the same sentence as CD4 in open-access papers (continued):
Sharing a sentence is not in itself a finding about the gene and the disease.
infection (continued). "This suggests that CD4+ TRM may be capable of clearing or controlling infection even before recruiting signals are generated in a magnitude large enough to attract circulating T cells to the site of infection." (PMID 30038624, 2018). "Notably, after the clearance of the infection, memory CD4+ T cells, B cells, DC, and macrophages form clusters beneath the epithelial layer of the vagina." (PMID 29904388, 2018). "Thus, the aim of this work was to study the effect of MIF/CD74 interaction on the phenotype and the function of primary HIV-infected MDMs, and how this axis determines the environment to modulate CD4+ T-cell permissiveness to infection." (PMID 29997630, 2018). "Notably, potent antagonism of SERINC5 enhanced the infectivity of virions produced in pre-activated CD4+ T cells only 2- to 3-fold but had up to 10-fold effects when PBMCs were stimulated several days after infection." (PMID 30125328, 2018). "A previous study using mice showed that after infection there is an increase in CD4+ T cells, interferon-γ, tumor necrosis factor-α and inducible nitric oxide synthetase that mediate the development of ileus necrosis and subsequently lead to the death of the mice in 13 days." (PMID 29324806, 2018). "Therefore, we sought to investigate the effects of LEC stimulation on the infection of activated CD4+ T cells." (PMID 30285810, 2018). "This difference was associated with global CD4+ T cell preservation, greater interferon gamma (IFN-γ) mRNA expression, and no cytotoxic T lymphocyte responses in co-infected cats relative to cats with a single FIV infection." (PMID 29677149, 2018). "25-HC improved the overall IFN-γ-producing cellular responses which are beneficial for controlling HIV-1 replication, but selectively suppressed IL-2/TNF-α-producing proinflammatory CD4+ T cells which are helpful for reducing inflammation and infection targets of HIV-1." (PMID 30524435, 2018). "In our experimental approach, the combination of the anti-DC-SIGN antibody conjugated to P25 with zymosan resulted in the strongest immune response in terms of cytokine production and also showed increased percentages of total KLRG1+ CD4+ T cells 5 days post-infection." (PMID 29662482, 2018). "Moreover, staining of 7-AAD and Annexin-V during infection showed comparable frequencies of dead/dying CD4+ and CD8+ T cells." (PMID 29749372, 2018). "The efficiency of cell-to-cell infection between CD4+ T cells has been related to a high-multiplicity of infection at the site of the cell–cell contact, probably leading to the integration, and accelerated viral gene expression of multiple proviruses in the target cell." (PMID 29515578, 2018). "Th1 CD4+ T cell responses are also important for control of infection with NTM." (PMID 30443245, 2018). "MHC-II-deficient mice (without CD4+ T lymphocytes) had stronger ability to control S19 infection than MHC-I-deficient mice (without CD8+ T lymphocytes), indicating that CD8+ T lymphocytes play a major role in the immunity against brucellosis infection." (PMID 29888294, 2018). "Once we knew IL-6 is involved in EC and LEC stimulation of resting CD4+ T cells, we set out to measure IL-6 levels at the end of infection (day 6 post infection) in T cells co-cultured with EC or LEC using ELISA, to see if IL-6 levels correlated with infection levels." (PMID 30285810, 2018). "Furthermore, in the cases of higher HIV-1 diversity in the blood during early infection, faster CD4 T cell decline were observed during chronic disease suggesting faster disease progression." (PMID 29346424, 2018). "Possibly this explanation may be due to the fact that poor adherence allow more viral replication which in turn increases infection of more CD4+ cells and ultimately depletion of their number." (PMID 29715323, 2018). "In these mice CD4+ T cell expansion and control of infection were restored." (PMID 30386330, 2018).
infection (continued). "A higher proportion of gut CD4+ T cells express HIV coreceptors and markers of T cell activation, which may enhance their susceptibility to infection or depletion during acute infection." (PMID 30440043, 2018). "Therefore, CD4 T cells (CellTrace Violet+) from IL-10 KO mice 7 days post-infection (p.i.)were adoptively transferred into infection-matched IL-10 KO recipients, which underwent transcardial perfusion and brain tissue collection 3.5 h later." (PMID 29866139, 2018). "M78 could be considered a systemic spread-specific infection module that couples CD4+ T cell evasion to virus production in myeloid cells." (PMID 29447285, 2018). "CXCR4 was first found to mediate CD4-independent infection by HIV-2 in 1996." (PMID 29581828, 2018). "Thus, unlike the concerted overexpression of all glucose transporters present in CD4+ T cells that we observed in response to infection with HIV-1, there is specificity in the upregulation of HK1." (PMID 29518929, 2018). "Despite MHC II degradation by CMVs, CD4+ T cells play an important role in infection control." (PMID 29447285, 2018). "The transfer of virus from DC to CD4+ T-cells is referred to as HIV trans-infection." (PMID 29415518, 2018). "The time between seroconversion and time at diagnosis was estimated using the formula [square root (CD4 at seroconversion)-square root(CD4 at HIV diagnosis)] / slope of CD4 decline.CD4 counts at the time of infection and the slope were computed in an age and ethnicity-dependent variable." (PMID 29420591, 2018). "The existence of a drug-limited compartment allowing new short-lived CD4 infections could affect long-term drug resistance." (PMID 30016329, 2018). "The outcome of infection is also dictated by the balance between CD4+ effector T cells and Tregs." (PMID 29315226, 2018). "The assay is conducted in primary CD4+ T cells isolated from healthy donors and cultured in human blood serum, and uses virus that is capable of only a single round of infection and that labels productively infected cells by expressing a fluorescent protein along with viral genes." (PMID 30129208, 2018). "Initially it was assumed HIV-mediated CD4 T cell depletion was occurring directly via viral cytopathic effects; however, other studies suggested the cells dying in lymph nodes in response to infection were uninfected bystander cells." (PMID 29614779, 2018). "Latently infected CD4+ T cell lines, primary CD4+ T cells, and induced human pluripotent stem cells (iPSCs) were incorporated with Cas9 and targeting gRNAs which prevents against the new infection by HIV-1." (PMID 30319822, 2018). "This suggests that in our study population, antibiotic treatment did not completely prevent the development of some degree of adaptive immunity with a CD4+IFN-γ response that might aid in more rapidly clearing infection in those who have reinfection." (PMID 30245688, 2018). "Indeed, it has been shown that this process occurs early in infection and is mediated by infected CD4+ T-cells." (PMID 30521629, 2018). "Collectively, these results suggest that TLR3 may be involved in modulating the recruitment of CD4 T-cells required to clear C. muridarum from the genital tracts of C57BL/6N mice during middle stages of infection." (PMID 29624589, 2018). "Unusually, EC2 had evidence of pre-infection HIV-specific CD4+ T cell responses." (PMID 29370775, 2018). "The number of these Ag85-specific CD4+ T cells expands during infection in both mouse strains." (PMID 29499041, 2018). "In addition, the differentiation of naïve CD4+ T cells into IL-17-secreting cells was reduced following hlyU mutant infection." (PMID 30283443, 2018). "Alternative mechanisms, including humoral responses or differential infection of T cell CD4+ subsets, might be an alternative mechanism of protection against HIV-mediated immune depletion." (PMID 29593044, 2018).
infection (continued). "Furthermore, when CD4+ T cell type 2 responses were measured in the lungs at day 10 post-infection, Retnla +/- mice exhibited significantly increased numbers of IL-4+ and IL-13+ CD4+ T cells." (PMID 30500858, 2018). "Also, studies in human volunteers have indicated that pre-existing CD4+ T cells correlate well to increased resistance against infection." (PMID 30271406, 2018). "Functionally, CD4+ T cells control infection by producing Th1 and Th17 cytokines." (PMID 30409122, 2018). "Therefore, weight gain early after cART-initiation often represents effective viral suppression and CD4+ recovery but also restoration of healthy pre-infection weight." (PMID 30542325, 2018). "Considering the preferential infection of α4β7high memory CD4+ T cells in the early stages of SIV/HIV infection, we reasoned that Act-1 might interfere with mucosal transmission." (PMID 29478152, 2018). "Indeed, there are increasing number of studies showing that the formation of CD4 TRM cells after natural infection mediates protective immunity against secondary exposure to the same pathogen." (PMID 30147701, 2018). "Third, CD4+ memory T cells can home to tissue sites of infection." (PMID 29438281, 2018). "In contrast, we have previously shown that in mice infected with the continuous systemically replicating lymphocytic meningitis virus (LCMV) Clone 13, IL-27R signaling promotes the accumulation of anti-viral CD4 T cells late post infection and is absolutely required for viral control." (PMID 30044874, 2018). "Initial studies investigating SIV target cells identified low levels of CCR5 expression as a common feature of several natural host species, which may limit infection of certain critical CD4+ T cell subsets, such as Tcm and Tscm." (PMID 29659623, 2018). "Also, IL-6 and TNFα has been shown to facilitate infection of resting CD4+ T-cells and to induce productive infection." (PMID 29997630, 2018). "The lessons learned from studying CD4+ T cell responses in adult mice provide a clear framework from which to ask questions about whether and how aging changes CD4+ T cell responses upon immunization or infection." (PMID 29864157, 2018). "Altogether, the viral tissue distribution could thus in part also explain the lower frequency of infection rate in TCM compared to CD4+ effector T cells in natural hosts." (PMID 29725327, 2018). "Although the overall fractions of CD4+ T cells of both mice groups were similar and significantly reduced by ~35% among spleen lymphocytes at 12 days after infection, T-bet+/CD44+ activated Th1 cells in the spleens of IFNAR KO mice were significantly higher than those of wild type mice." (PMID 30233599, 2018). "Subdued induction of CD200 by LdCen−/− compared to LdWT infection suggested that blocking this signaling could divert more CD4+ T cells to acquire multi-functionality." (PMID 29915577, 2018). "Importantly, at both periods of infection an increased number of activated CD4+CD25+ and CD8+CD69+ T cells were found in the lungs of Treg depleted mice." (PMID 30410119, 2018). "LEC stimulation also increased infection rates in activated CD4+ T cells." (PMID 30285810, 2018). "This patient was 42 years old (with probably past HBV resolved infection), has 16 CD4 cells/mL and combined with their HIV status, we can hypothesize about loss of antibodies against HBV virus, as supported by multiple studies." (PMID 29315352, 2018). "Exosomes bearing viral antigens deliver their cargo to CD4+ T cells and provoke infection." (PMID 30416610, 2018). "In addition, certain CD4+ T cell phenotypes that promote HIV attachment and invasion, such as β7Hi, predict the risk of infection and disease progression." (PMID 30534128, 2018).
infection (continued). "Although CD8+ T-cells and B cells had little divergence in the two groups, the CD4+/CD8+ T-cell ratio declined more rapidly in the stHIV-1sv infected NPMs compared to the HIV-1NL4−R3A infected NPMs during the primary infection, consistent with the respective viral loads in the two groups." (PMID 30210504, 2018). "Moreover, the conditioned environment generated by MIF/CD74 interaction in infected MDMs promotes CD4+ T-cell permissiveness to infection." (PMID 29997630, 2018). "The two groups were matched for duration of infection, viral loads, and CD4 counts." (PMID 30120121, 2018). "As such, the reliability of the CD4 count as a marker of recent infection (CD4 > 500 cells/mm3) may have implications for the WHO-TS in DC." (PMID 30309385, 2018). "FVB mice depleted of both CD4+ and NK cells also remained resistant to infection." (PMID 30283457, 2018). "Age at the time of diagnosis (HR = 1.003, 95% CI = 1.000–1.006), smoking (HR = 2.338, 95% CI = 1.236–4.424), baseline Scr ≥5.74 mg/dl (HR = 2.153, 95% CI = 1.323–3.502), CD4+ T cell< 281 ul (HR = 1.813, 95% CI = 1.133–2.900), and use of intravenous CYC were independent risk factors of infection." (PMID 29902982, 2018). "First, 25 days after mouse infection, CD4+ cells were isolated from spleens and cocultured with CD8-depleted uninfected autologous spleen cells to allow virus spread, some cultures contained ABC, to distinguish provirus in donor cells from that in newly infected cells." (PMID 29879225, 2018). "Interestingly, HA present on the surface of CD44-expressing primary CD4+ T cells and T cell lines has been observed to reduce direct binding and infection of CD44-containing HIV-146." (PMID 29934525, 2018). "A marked upregulation of OX40 is observed on Plasmodium specific CD4+ T cells that are generated in both human and rodent malaria blood stage infections and, in rodent studies, α-OX40 treatment was shown to increase parasite-specific memory CD4+ T cells resulting in a reduced blood-stage infection." (PMID 30073152, 2018). "In addition, CD4+ T cells exposed to IFN-γ in the early phase of infection tend to differentiate into Th1 type effector cells, rather than Th2 cells, leading to a proinflammatory state." (PMID 29720984, 2018). "In Italy, despite HIV testing and healthcare being free of cost for the individual, more than half of the ca 4,000 people diagnosed with HIV annually are diagnosed with a CD4 count < 350 cells/mm3, and ca 40% are at the symptomatic stage of infection when diagnosed." (PMID 29667577, 2018). "A lower frequency of EBV-specific IFN-γ+/TNF-α+ CD4+ T cells has been described in HIV+ patients at early stages of infection and under ART when compared to that of responses to CMV and Mycobacterium tuberculosis, which are superior in frequency and multifunctionality." (PMID 30337929, 2018). "Collectively, these findings indicate that infection with the fbp1Δ mutant induces enhanced recruitment of innate and adaptive immune cells, as well as increased induction of Th1 and Th17 responses, and lower Th2 CD4+ T cell responses." (PMID 29317510, 2018). "By budding at the tip of filopodia in DCs, HIV-1 could be able to tether concomitantly several neighboring CD4+ T cells, leading to viral transfer and infection of the target T cells." (PMID 29515578, 2018). "We found that IL-27 enhanced the number of antiviral CD4 T cells upon infection." (PMID 30044874, 2018). "Our studies revealed that most of the antigen-specific pulmonary CD4 T cells are localized to the tissue as compared to the vasculature and that the extensive degree of epitope-specific diversity observed in the dLN is maintained in the lung after infection." (PMID 29681900, 2018).
infection (continued). "At later timepoints following infection (weeks 16 and 22), therapeutic immunization induced a significantly higher frequency of CD4+ T cells producing CD154, GM-CSF, IFN-γ, IL-2, and TNF-α at 16 and 22 weeks post infection compared to RHZ-treated mice with ex vivo ID93 antigen stimulation." (PMID 29795025, 2018). "Furthermore, we measured the number of NK and CD4 T cells in the lungs after infection through flow cytometry and found that the KO mice had more NK and CD4 T cells accumulated in the lungs compared to that of WT mice." (PMID 30248149, 2018). "In particular, since MV-specific CD4+ and CD8+ effector T cells are susceptible to infection (although the latter at a potentially lower rate), their proliferation may counterintuitively facilitate viral growth by increasing the target cell population." (PMID 30592772, 2018). "Another study showed the magnitude of the TBEV-specific CD4+ T cell responses to capsid protein and E protein were significantly lower in patients with natural infection than in individuals immunized with an aluminum hydroxide-adjuvanted formalin-inactivated TBEV vaccine." (PMID 30340377, 2018). "First, we found no statistically significant changes in the number of splenic CD4+ or CD8+ T cells in B6.Bach2ΔT mice prior to infection, although a small, consistent decrease in the frequency of these cell populations in the spleen was noted, compared to controls." (PMID 30459773, 2018). "This trans-infection pathway in DCs helps with dissemination of HIV-1 to CD4 + T-cells." (PMID 29632536, 2018). "These epitope-dependent preferences in CD4 T cell differentiation persist independently of whether the epitopes are introduced via infection, protein vaccination, or in a completely heterologous protein vector." (PMID 29681900, 2018). "Having confirmed the cell type specific deletion of Il-27p28 in both genetic models, we next, analyzed KLRG1 and GrzA expression at different time points post infection to investigate which cellular source was important for IL-27 mediated regulation of a cytotoxic phenotype in antiviral CD4 T cells." (PMID 30044874, 2018). "In addition, it has been proposed that MHCII is also expressed by type II alveolar pneumocytes during infection, enabling CD4+ T cells to target a minor population of infected cells in the lung tissue by direct cytotoxic mechanisms themselves." (PMID 29587436, 2018). "Our interpretation of these results is that platelets become activated by CFA or pathogens (bacteria) and produce a number of pro-inflammatory factors that support the proliferation and differentiation of CD4 T cells toward Th1 and Th17 at the site of immunization or infection." (PMID 29599771, 2018). "Because we routinely expand the activated CD4+ T cells for a period of up to four days prior to the infection, to obtain enough HIV-1 infected cells for downstream analyses, we first monitored the expression levels of the GLUT proteins over this period of time." (PMID 29518929, 2018). "We evaluated whether differences in viral diversity at very early/early infection influenced viral load kinetics (following viral set point to initiation of cART) and CD4 T cell counts during asymptomatic disease and up to initiation of cART." (PMID 29346424, 2018). "Altered differentiation of CD4+ T cells in response to infection with the fbp1Δ mutant." (PMID 29317510, 2018). "Interestingly, the percentage and the number of CD4 T cells constantly increased over the course of infection to reach a peak at d35 p.i. in both groups of mice." (PMID 29472618, 2018). "Increased expression of PD-1 in spleen CD4+ T cells was observed in the initial acute stage of infection, peaked at week 6, and followed by a slight decline thereafter with significant difference to the baseline expression level in the CD4+ T cells of normal mice." (PMID 30093899, 2018).